LBP (lipopolysaccharide binding protein)
Diseases named in the same sentence as LBP in open-access papers (continued):
Sharing a sentence is not in itself a finding about the gene and the disease.
cardiovascular disease (10 papers, 2017 to 2025). "Several studies have shown LPS, LBP and sCD14 to be elevated in individuals with cardiovascular disease or populations at high risk of developing cardiovascular events." (PMID 39563343, 2024). "LBP encodes a lipopolysaccharide binding protein, and higher levels of serum LBP have been reported to be associated with enhanced risk of cardiovascular diseases." (PMID 36274122, 2022). "In previous studies on the LPS-related factors, sex-adjusted association was observed between LBP/soluble CD14 and aortic stiffness, carotid intima-media thickness, and cardiovascular disease." (PMID 28486964, 2017). "We found 6 proteins that mediated the PGSCAD’s effect on MACE in EXSCEL (C9, LBP, ITIH4, APOM, CES1, and HS6ST2), providing supporting evidence that they might serve as biomarkers for cardiovascular disease in patients with T2D52–54." (PMID 40032831, 2025).
inflammation (10 papers, 2017 to 2025). Aberrant reaction of the microcirculation characterized by movement of fluid and leukocytes from the blood into extravascular tissues. "We found a significant positive correlation between the influx of macrophages (CD68+) in the orbital tissue and serum LBP level (r = 0.4, p = 0.043), linking a “leaky” gut with orbital inflammation." (PMID 38107520, 2023). "The highest LBP levels were found in patients with chronic gut inflammation suggesting a relation between LBP levels and gut inflammation in axSpA patients." (PMID 34560894, 2021). "Markers of chronic inflammation (e.g. LBP and CRP) as well as fecal calprotectin and fecal IgA were not significantly different between the groups." (PMID 29211757, 2017). "Analysis of bacterial species composition and KEGG function showed that high-dose intragastric PM leads to colonic intestinal inflammation by increasing the abundance of various bacteria in the jejunum, ileum, and colon and increasing the levels of LBP and IL-1β." (PMID 38535466, 2024). "However, in axSpA cohort 3 with histological assessment of gut inflammation, we found highest LBP levels in patients with signs of chronic gut inflammation suggesting a relation of LBP levels to gut pathology in axSpA." (PMID 34560894, 2021). "A significant increase in LPS, LBP, sIgA and FC in the HFD group demonstrated that the intestinal permeability was damaged and intestinal inflammation occurred due to the high fat diet." (PMID 33802755, 2021). "To determine whether LBP levels are related to intestinal inflammation in axSpA patients, we analyzed LBP levels in axSpA patients of the GIANT cohort in whom presence of intestinal inflammation was assessed by colonoscopy and microscopic evaluation." (PMID 34560894, 2021).
infectious disease (6 papers, 2017 to 2024). A disorder directly resulting from the presence and activity of a microbial, viral, or parasitic agent in humans. "It has been shown that pulmonary LBP is upregulated following LPS-mediated injury, and circulating LBP levels are increased in several infectious diseases, such as septic shock and acute lung inflammation." (PMID 28634422, 2017).
respiratory disease (3 papers, 2013 to 2023). "Others have shown that the concentration of SAA, Hp and LBP in TA increases with respiratory disease and salivary Hp increases after dehorning." (PMID 38007540, 2023). "LBP changes in BALF were both associated with changes in respiratory score and systemic LBP response, and LBP seems to be a very promising candidate for a local marker of respiratory disease in calves." (PMID 38007540, 2023). "SAA, Hp and LBP in TA increases in calves with respiratory disease, but a validation of the used assays in this material have not been performed." (PMID 38007540, 2023). "Receiver operating characteristics analyses using a 5-protein panel (CFHR5, LRG1, CRP, LBP, and SAA1) exhibited discriminatory power in distinguishing TB from other respiratory diseases (AUC = 0.81)." (PMID 32780727, 2020).
neurodegenerative disease (1 paper, 2024). A disorder of the central nervous system characterized by gradual and progressive loss of neural tissue and neurologic function. "Strategies that modulate the interaction between LBP and the innate immune response could help maintain BBB integrity and reduce neuroinflammation, possibly providing protective effects in neurodegenerative diseases." (PMID 39796152, 2024).
retinopathy (1 paper, 2023). "We showed in T1D diabetic individuals that gut permeability correlates with disease severity, as the highest levels of PGN, FABP-2 and LBP were seen in the most advanced retinopathy." (PMID 36902558, 2023).
LBP also shares sentences with these, for which no sentence is quoted: acute appendicitis (4 papers); Cognitive impairment (4); psoriasis (4); endothelial dysfunction (3); fungal infections (3); immune dysfunction (3); portal hypertension (3); acute kidney injury (2); Autoimmunity (2); cardiomyopathies (2); dementia (2); End Stage Liver Disease (2); heart failure (2); hepatocellular carcinoma (2); neutropenia (2); obstructive sleep apnea (2); osteosarcoma (2); vitamin D deficiency (2); abscesses (1); acute myocardial infarction (1); adenocarcinoma (1); alcohol (1); angioimmunoblastic T-cell lymphoma (1); atrophic gastritis (1); autism (1); autoimmune disease (1); bacterial meningitis (1); behavioural disorders (1); bipolar disorder (1); blood pressure (1).
A further 72 diseases each share a sentence with LBP in 1 paper.